LEP (leptin)
Diseases named in the same sentence as LEP in open-access papers (continued):
Sharing a sentence is not in itself a finding about the gene and the disease.
Obesity (continued). "Several markers of obesity and inflammation, including CRP (marker of inflammation), insulin (marker of insulin resistance), and leptin (marker of adiposity) were measured to evaluate their potential associations with estradiol or estrone levels." (PMID 32566743, 2020). "In human NK cells, short-term exposure to leptin led to increased anti-tumor activity and long-term exposure resulted in impaired anti-tumor function, suggesting that NK cell activity in the context of obesity might be impaired in the setting of chronic hyperleptinemia." (PMID 33604295, 2020). "In obesity, homeostatic model assessment of insulin resistance (HOMA-IR) values are commonly increased and leptin is elevated, too." (PMID 33117276, 2020). "The deletion of NCOA1 in POMC neurons attenuates their depolarization by leptin, decreases POMC expression, and increases food intake, which accelerates high-fat diet-induced obesity." (PMID 32449767, 2020). "Accordingly, the KO mice were resistant to long-term HFD-induced obesity and showed an improvement in HFD-induced leptin resistance." (PMID 32560726, 2020). "We have demonstrated a novel role of PAI-1 in exacerbating hypothalamic leptin resistance, resulting in HFD-induced obesity." (PMID 32670063, 2020). "In contrast, brain knockout or central pharmacological inhibition of TLR4 or IKKβ/NF-κB prevents hypothalamic inflammation, improves leptin sensitivity and protects against HFD-induced obesity." (PMID 32760236, 2020). "MCF-10A cells were treated with 50 ng/mL of leptin and/or 5 ng/mL of FGF2 to simulate the physiologic circulating concentrations of these growth factors in obesity." (PMID 33019728, 2020). "This study investigated the effects of RIF on gut hormones (leptin, ghrelin, GLP-1, PYY, and CCK) in males with obesity in Tunisia." (PMID 32756479, 2020). "While the EpiCAT expression of resistin, leptin and TNF-α increase in obesity, the expression of adiponectin is markedly reduced." (PMID 33282920, 2020). "Clearly, more study is essential for a full understanding of the sex differences in the effects of leptin on SNA and how this is modified with obesity." (PMID 32160920, 2020). "An increase in leptin and insulin levels has been blamed to explain the decrease in ghrelin levels in individuals with obesity; it has also been suggested that this alteration could represent a physiological adaptation of the body to obesity once a positive energy balance is reached." (PMID 32442310, 2020). "To further confirm the anti-obesity effects of CO + RF in the OVX mouse model, we examined two obesity-related hormones (leptin and insulin) from the left ventricle of mice." (PMID 32019227, 2020). "Compared to the normal tissues, five obesity-related genes (POMC, LEP, PCSK1, MTCH2, and GPR120) did show a similarity alteration of DNA methylation patterns in different cancer tissues." (PMID 33299884, 2020). "Participants with overweight and obesity showed significantly higher HOMA-IR scores and leptin levels than participants with normal weight." (PMID 32721994, 2020). "This is consistent with previous studies showing hyperleptinemia, central leptin resistance and upregulated AMPK activity in programmed obesity." (PMID 33138074, 2020). "This review is focused on leptin and LEPR signaling in the (dys-)regulation of the cardiovascular system in the context of obesity and metabolic syndrome." (PMID 32655492, 2020). "Thus, obesity status may modify leptin levels directly or indirectly through gene transcription." (PMID 31914480, 2020). "Moreover, leptin levels are increased in OSA patients and correlates with OSA severity, suggesting that part of the CB overactivity and altered hypoxic ventilatory responses in OSA and obesity might be associated with a direct action of leptin in the CB." (PMID 32756352, 2020). "In obese breast cancer patients with often chronically elevated leptin levels, leptin NILCO signalling seems to provide a link between obesity and cancer." (PMID 32033341, 2020).
Obesity (continued). "Downregulation of Scd1 attenuates leptin-induced phosphorylation of signal transducers and activator of transcription 3 (STAT3), leading to obesity." (PMID 33282902, 2020). "Leptin-induced NOTCH signaling contributes to BC proliferation, metastasis, and correlates to BC development in the context of obesity." (PMID 32326381, 2020). "Literature data suggest that possible differences in LEP and LEPR expression in peripheral tissues, as well as species differences in obesity condition, should be taken into consideration." (PMID 33316917, 2020). "Therefore, it could be speculated that the severity of psoriatic lesions is mostly associated with increased inflammation in the course of obesity that could partially be related to leptin activity rather than be a direct effect of enhanced leptin levels." (PMID 33008429, 2020). "Compared to the normal tissues, the five obesity-related genes (POMC, LEP, PCSK1, MTCH2, and GPR120) showed a similarity alteration of DNA methylation patterns in different cancer tissues." (PMID 33299884, 2020). "The G-308A polymorphism was also found to be associated with insulin sensitivity and increased production of leptin, suggesting an impact of TNF-α gene on obesity and obesity-related health complications." (PMID 30900134, 2020). "It was also proven that curcumin interrupts leptin signaling and activates PPAR-γ in rat hepatic stellate cell growth, and it is able to increase adiponectin expression in a mouse model of obesity and diabetes." (PMID 32455840, 2020). "Obesity enhances the renin-angiotensin-aldosterone system (RAAS), leptin-induced activation of the sympathetic nervous system (SNS), tubular sodium reabsorption, and volume expansion, leading to hypertension." (PMID 33121167, 2020). "Evidence also supports the role of obesity-induced inflammation (IL-6, TNF-α, and leptin) in Tamoxifen® and anti-VEGF acquired breast cancer drug resistance." (PMID 32257945, 2020). "Similar results were obtained for correlation with markers of obesity (insulin, CRP, and leptin) with estradiol and estrone (−0.15 to 0.12; p = 0.11–0.82)." (PMID 32566743, 2020). "All the analyzed groups had a statistically significant positive correlation between leptin and BMI and a negative correlation between ghrelin and adiponectin and BMI, which are in accordance with earlier studies, thus confirming their potential for the determination of the obesity risk." (PMID 32085704, 2020). "Therefore, this study intended to further assess the effect of different doses of leptin in pig embryo implantation using primary porcine endometrium epithelium cells (PEECs), contributing to the understanding of the mechanisms of reproductive disorders in obesity." (PMID 32906753, 2020). "The novel findings of this study that serum visfatin and leptin were positively related to xenograft tumor growth were consistent with the notion that adipokines and other growth factors secreted on the background of obesity may prompt cancer cell survival and tumor growth." (PMID 33381605, 2020). "Another mechanism may be related to leptin, which partially mediates the process of cardiac hypertrophy by the mitogen-activated protein kinase (MaPK p38), which regulates various cellular processes; however, our results showed that RT promotes reduction in leptin levels in obesity condition." (PMID 32714085, 2020). "In fact, such forms of obesity may most closely reflect the obesity phenotypes in many humans (compulsive eating behavior combined with hypercaloric diet and accompanied by functional leptin resistance), while ob/ob and HFD models used separately display some limitations." (PMID 31878078, 2019). "Fibrates and thiazolidinediones (TZDs) activate intracellular nuclear receptors such as PPARγ and TZDs, and reduce the expression of leptin and TNF-α, thereby reducing the inflammatory process by obesity." (PMID 30818882, 2019).
Obesity (continued). "Moreover, since leptin has been shown to directly stimulate the catecholamine synthesis and secretion, there might be a direct link between increased basal norepinephrine and the hyperleptinemic condition in obesity." (PMID 31682617, 2019). "Overall, this is the first study revealing the exact dynamic of hypothalamic eCBs during the development of obesity in DIO models, and these temporal changes correlated positively to BAT thermogenesis and negatively to circulating eCB, leptin, and body weight." (PMID 31138606, 2019). "Impaired transport across the BBB, endoplasmic reticulum (ER) stress, obesity-induced chronic inflammation, and hyperleptinemia-induced suppressor of cytokine signaling 3 (SOCS3) transactivation are regarded as factors of leptin resistance." (PMID 31408957, 2019). "We have shown that obesity's involvement in OA is not only limited to the mechanical weight exerted on the joints (mechanical hypothesis), but also induces an inflammatory state by different mechanisms, including increased leptin expression, compromised gut mucosa, and/or gut microbiota disruption." (PMID 31781260, 2019). "Interestingly, intra-cerebroventricular administration of BMP7 was shown to ameliorate the HFD-associated metabolic complications, suggesting that BMP7 may be explored as an attractive obesity therapeutic for diet-induced obesity and leptin-resistant conditions.." (PMID 31831718, 2019). "Among obese persons, a higher degree of obesity often results in lipid metabolism abnormalities such as elevated serum TG, TC, LDL-c and leptin levels and decreased HDL-c and adiponectin levels." (PMID 30691060, 2019). "We also evaluated some metabolic (leptin, insulin, glucose) and neuroendocrine and endocrine (Pomc and Npy expression, HPA axis) parameters related to diet-induced obesity and stress, some of which modulate the activity of TRH neurons in the PVN." (PMID 31354623, 2019). "Our data, showing dysregulation of leptin and adiponectin serum levels in the HFD animals, confirm the link between these adipokines, obesity-related metabolic disorders, and inflammation." (PMID 31798417, 2019). "In obese subjects (n = 173), the degree of obesity and BMD were related to IL-6 levels (in males), osteocalcin (in females), C-reactive protein (CRP), and leptin indicating that adiposity and systemic inflammation are associated with low BMD." (PMID 30792697, 2019). "Further indicative of obesity and metabolic dysregulation, miR-146a-/- mice on HFD developed elevated serum Leptin protein levels." (PMID 30768595, 2019). "Upon its discovery, it was extremely reasonable to expect that further increases in leptin levels occurring with “excess adiposity” might further suppress appetite and increase energy expenditure, thereby serving as a physiologic “lipostatic” signal to resist obesity." (PMID 30357355, 2019). "Thus, this cellular macrophage system provides only limited support for leptin’s effect on macrophage autophagy, and given the modest inhibitory effect – could not explain contribution to the activation of whole adipose tissue increased autophagy in obesity." (PMID 30676227, 2019). "Inflammation in obesity is manifested by increased circulating levels of classical pro-inflammatory cytokines, such as TNF and altered levels of adipokines, including leptin, resistin, and adiponectin." (PMID 31024226, 2019). "However, the vast majority of obese patients exhibit an increase in circulating leptin levels (perhaps as a failing homeostatic mechanism in which leptin levels are upregulated yet fail to tame appetite), meaning that leptin deficiency is not a major pathogenic factor in obesity." (PMID 31656948, 2019). "In patients with obesity, several biochemical parameters are altered including FFA, TG, cholesterol, vitamin D, insulin, and leptin." (PMID 31207920, 2019).
Obesity (continued). "In line with previous studies, our data indicate that anti-obesity effects of Rv-PEM01-99 are related to the suppression of intra-abdominal fat and leptin levels." (PMID 31548839, 2019). "Pro-inflammatory hormones and cytokines (leptin, tumor necrosis factor (TNF)-α, and interleukin (IL)-6) rise in obesity." (PMID 31817534, 2019). "In Wistar rats induced to obesity by an HFD, the plasma analyses demonstrated that melatonin attenuated the increase of the leptin observed in obese animals." (PMID 31489938, 2019). "Given the rise of obesity and T2DM in juveniles, further study is needed to elucidate the clinical implications of leptin dysregulation on long-term bone and joint health." (PMID 30697359, 2019). "Galantamine treatment of mice with established obesity (after 8 weeks on a high-fat diet) significantly lowers plasma IL-6, CCL2, leptin, and resistin levels, and reduces body weight, food intake, and abdominal white adipose depots." (PMID 31024226, 2019). "There is also an increase in secretion of pro-inflammatory hormones such as the thyroid hormone and cytokines (leptin, tumor necrosis factor (TNF)-α, and interleukin (IL)-6) in obesity." (PMID 31817534, 2019). "In a study of diet-induced obesity, the genetic ablation of Prkci in proopiomelanocortin (POMC) neurons disrupted leptin action and increased glucose intolerance, insulin resistance and obesity in male mice fed high-fat diets." (PMID 32269838, 2019). "However, in most dietary obesity rodent models, hyperleptinemia was documented and explained by occurrence of systemic leptin resistance and reduced physiologic action of leptin; this may help to describe the affected LH and gonadotropin level in our rat model." (PMID 32082253, 2019). "Obesity was found to be also associated with reduced white matter integrity, particularly in the genu, splenium, and fornix, suggesting a possible role for adiposity in white matter dysfunction and the associated cognitive deficits, however, leptin level was not evaluated in this study." (PMID 31354416, 2019). "We sought to investigate the possible role of the pro-inflammatory state on such alteration, considering the effect of the expression of markers, such as leptin and IL6, which are notably high in obesity." (PMID 31664059, 2019). "Additionally, leptin is a major stimulus for the production of aldosterone in obesity, and might be responsible for the exacerbated mineralocorticoid receptor signaling in obesity-related HF." (PMID 31428620, 2019). "An increase in ghrelin and a decrease in leptin could lead to decreased energy expenditure, impaired glycemic control, increased appetite, and elevated caloric intake; furthermore, increased energy consumption might further trigger obesity and the development of metabolic syndrome." (PMID 31404954, 2019). "Previous anti-obesity effects on COS and CTS were primarily focused on their effects on leptin resistance and fat formation." (PMID 31817377, 2019). "The results indicated that DPHC effectively regulated the obesity-related blood metabolic parameters in HFD-induced obese mice displayed in reducing TG, LDL-C, leptin, and AST levels, and increasing HDL-C levels." (PMID 31717668, 2019). "The protein and mRNA levels of HuR were significantly decreased in WAT and BAT from the leptin mutant (ob/ob) and HFD-fed mice, the models of obesity and type 2 diabetes, as compared with their controls." (PMID 31147543, 2019). "Systemic inflammatory impacts of adipokines including LEP, resistin, and adiponectin (ADIPO) among others mediate the relationship between obesity and osteoarthritis." (PMID 31878053, 2019). "The exact impacts of leptin and ObR-b on IMB and gut microbiota on obesity with AP need further experiments." (PMID 30635594, 2019). "This review will focus on DNA methylation as a possible mechanism regulating, specifically, leptin and insulin signaling within the hypothalamic ARC during the pathogenesis of obesity." (PMID 31660128, 2019).
Obesity (continued). "Several of these genes, like LEP, PPARA, PPARD, LPIN1, SREBP1, and ADIPOQ are described in obesity in both humans and mice." (PMID 31921306, 2019). "When the correlation study was performed separately in relationship to obesity, it was found in lean girls that pro-UGN levels were negatively correlated with age, Tanner stage, weight, height, BMI, waist circumference, insulin leptin and testosterone." (PMID 30266914, 2018). "Its importance is clearly illustrated by the extreme obesity observed in the ob/ob mouse (C57BL/6J-Lepob), which cannot produce functional leptin." (PMID 29975721, 2018). "Recent data show that in PC and other cancer types the adipokine leptin can modulate Notch/RBP-Jk signaling, thereby, linking the pandemic obesity with cancer and chemoresistance." (PMID 30004402, 2018). "In this study, we aimed to explore the correlation between leptin and OPN in eosinophilia of AR children with obesity." (PMID 30473626, 2018). "Therefore, leptin could be a link between obesity and the prevalence of cardiovascular diseases." (PMID 30154842, 2018). "Factor 1 (“EMS-suspect” score) positively correlated with variables typically characteristic of EMS including obesity measurements, MIRG, leptin, and triglycerides." (PMID 30001422, 2018). "Factor 1 correlated positively with variables typically elevated in obesity and EMS, including AVG BCS, NC/H, HG/Height, triglycerides, leptin, and MIRG." (PMID 30001422, 2018). "Furthermore, leptin could provide a functional link between obesity and CVD." (PMID 30584543, 2018). "To unravel the mechanism as to how obesity impairs the outcome of DTIC therapy in melanoma, we investigated the specific role of leptin and resistin as their levels in serum are elevated under obese condition." (PMID 29568521, 2018). "For example, deletion of protein tyrosine phosphatase 1B and T-cell protein tyrosine phosphatase enhances leptin signaling in POMC neurons and prevents diet-induced obesity by increasing WAT browning and energy expenditure." (PMID 29632515, 2018). "HPA axis, gonadal, growth hormone, leptin, SNS, and adrenergic, dopaminergic, and serotoninergic central pathways, all seem interconnected and involved with obesity." (PMID 30108549, 2018). "Thus, it suggests that the leptin resistance may occur in striped hamsters refed high-fat diet, which may impair the control of energy intake, consequently resulting in hyperphagia and development of obesity." (PMID 29343842, 2018). "Actually, substrate trapping trials using catalytically inactive PTP1B D181A confirmed that leptin-activated JAK2 is considered a PTP1B substrate, and that leptin signaling reduction is an obesity resistance mechanism in PTP1B null mice." (PMID 30558294, 2018). "Similar to leptin, MCP-1 is significantly involved in the pathogenesis of several metabolic disorders including inflammation, obesity and diabetes." (PMID 29785210, 2018). "In this review, we discuss the effects of obesity and diabetes-induced inflammation on the BBB, the roles played by leptin and insulin resistance, as well as BBB changes occurring at the molecular level." (PMID 30618559, 2018). "Moreover, our finding of negative correlations between the association rates of leptin-reactive IgG and obesity markers in healthy controls, but not in obese and diabetic patients suggest a protective role of such autoAbs and their potential contribution to leptin-mediated effects." (PMID 29795184, 2018). "Single nucleotide variants (SNVs) in the leptin receptor gene (LEPR) and other genes in the leptin-melanocortin hypothalamic pathway (LEP, POMC-ADCY3, PCSK1, MC4R, BDNF) have been reported in humans with obesity-related traits, and in children specifically." (PMID 30126176, 2018). "Recent evidence, however, concludes that a series of distinct pharmacological compounds can potentiate leptin signaling and empower its weight-lowering abilities in HFD-induced obesity." (PMID 29748097, 2018).